ATP1B3 (ATPase Na+/K+ transporting subunit beta 3)
Description:
This is the non-catalytic component of the active enzyme, which catalyzes the hydrolysis of ATP coupled with the exchange of Na(+) and K(+) ions across the plasma membrane. The exact function of the beta-3 subunit is not known.
Synonyms: ATPB-3; CD298; FLJ29027
Tractability: Small molecule: a drug acting on it is in phase 2 or 3 trials; a high-quality ligand is known; it belongs to a druggable protein family. Antibody: its Gene Ontology location is reachable by antibodies, with high confidence; UniProt places it where antibodies can reach, with medium confidence; UniProt predicts a signal peptide or a membrane-spanning region; the Human Protein Atlas places it where antibodies can reach. PROTAC: ubiquitination databases record sites on it; its protein half-life has been measured.
Target class: P-type ATPase; Sodium potassium ATPase; Primary active transporter; Transporter
Safety:
Unwanted effects reported when the protein is acted on. In parentheses: how it was acted on, where the effect was seen, and who reports it.
atrioventricular block (inhibition, acute dosing; renal, cardiovascular; source: Lynch et al. (2017))
cardiac arrhythmia (inhibition, acute dosing; renal, cardiovascular; source: Lynch et al. (2017))
decreased heart rate (inhibition, acute dosing; renal, cardiovascular; source: Lynch et al. (2017))
increased cardiac contractility (inhibition, acute dosing; renal, cardiovascular; source: Lynch et al. (2017))
increased urinary sodium excretion (inhibition, acute dosing; renal, cardiovascular; source: Lynch et al. (2017))
increased urine excretion (inhibition, acute dosing; renal, cardiovascular; source: Lynch et al. (2017))
ventricular fibrillation (inhibition, acute dosing; renal, cardiovascular; source: Lynch et al. (2017))
vomiting (inhibition, acute dosing; renal, cardiovascular; source: Lynch et al. (2017))
Gene: Protein-coding gene on chromosome 3 (141,876,124 to 141,926,549, forward strand). Ensembl gene ENSG00000069849.
Subcellular location: Apical cell membrane; Basolateral cell membrane; Melanosome
Subcellular location (Human Protein Atlas): Plasma membrane
Pathways (Reactome):
Disease: Potential therapeutics for SARS
Hemostasis: Basigin interactions
Muscle contraction: Ion homeostasis
Transport of small molecules: Ion transport by P-type ATPases
Gene Ontology:
Molecular function: ATPase activator activity; ATPase binding; protein binding; protein-macromolecule adaptor activity; transporter activator activity
Biological process: intracellular potassium ion homeostasis; intracellular sodium ion homeostasis; membrane repolarization; positive regulation of potassium ion import across plasma membrane; positive regulation of sodium ion export across plasma membrane; potassium ion import across plasma membrane; potassium ion transmembrane transport; protein localization to plasma membrane; protein stabilization; sodium ion export across plasma membrane; sodium ion transmembrane transport; potassium ion transport; sodium ion transport
Cellular component: extracellular exosome; plasma membrane; sodium:potassium-exchanging ATPase complex; sperm flagellum; apical plasma membrane; basolateral plasma membrane; cytoplasm; melanosome
Genetic constraint (gnomAD): Loss-of-function variants: 7 observed, 21.24 expected, observed/expected ratio (o/e) 0.33, 90% interval 0.19 to 0.62. The upper end of that interval is the gene's LOEUF score, 0.62, which puts it in group 2 of 6, group 1 being the genes least tolerant of losing a copy. Missense variants: 219 observed, 280.5 expected, observed/expected ratio (o/e) 0.78, 90% interval 0.7 to 0.87. Synonymous variants: 99 observed, 101.35 expected, observed/expected ratio (o/e) 0.98, 90% interval 0.83 to 1.15.
Homologues: Orthologues: chimpanzee ATP1B3 (100% identical), macaque ATP1B3 (99% identical), dog ATP1B3 (83% identical), guinea pig Atp1b3 (82% identical), rabbit ATP1B3 (81% identical), mouse Atp1b3 (73% identical), rat Atp1b3 (64% identical), rat AABR07070238.1 (63% identical), tropical clawed frog atp1b3 (57% identical), zebrafish atp1b3a (53% identical), zebrafish atp1b3b (52% identical). Paralogues in human: ATP1B2 (48% identical), ATP1B1 (39% identical), ATP1B4 (36% identical), ATP4B (36% identical).
Diseases named in the same sentence as ATP1B3 in open-access papers:
ATP1B3 is named in the same sentence as 35 diseases in open-access papers, as found by Europe PMC text mining. Sharing a sentence is not in itself a finding about the gene and the disease. The quoted sentences say what the papers report.
gastric cancer (7 papers, 2017 to 2025). A primary or metastatic malignant neoplasm involving the stomach. "Hence, ATP1B3 may function as a pleiotropic modulator of gastric cancer progression, although the underlying mechanisms of ATP1B3 in gastric tumourigenesis need to be further elucidated." (PMID 29137423, 2017). "The study has displayed that ATP1B3 expression was increased in gastric cancer tissues and was closely related to related to gastric cancer patients’ clinical characteristics." (PMID 33868261, 2021). "Mechanically, ATP1B3 promotes the malignant progression of gastric cancer via the phosphatidylinositol 3-kinase (PI3K)/protein kinase B (AKT) signaling pathway." (PMID 32684846, 2020). "Overexpressed ATP1B3 in gastric cancer promotes tumor proliferation, invasion, anti-apoptosis and cell-cycle arrest." (PMID 32684846, 2020). "In gastric cancer cells knockdown of ATP1B3 expression inhibited proliferation, colony-formation ability, migration, and invasion and induced apoptosis via the PI3K/AKT pathway." (PMID 32054977, 2020). "Next, we investigated the clinicopathological relevance of ATP1B3 expression for gastric cancer patients." (PMID 29137423, 2017). "PI3K, AKT and phosphorylation of AKT were reduced in both gastric cancer cell lines after ATP1B3 knockdown." (PMID 29137423, 2017). "The ATP1B3 protein was predominantly localized in cell membranes in both gastric cancer and normal tissues." (PMID 29137423, 2017). "ATP1B3 expression was increased in gastric cancer samples, and knockdown of ATP1B3 expression inhibited gastric cancer cell proliferation, colony-formation ability, migration, and invasion and induced gastric cancer cell apoptosis via the PI3K/AKT pathway." (PMID 29137423, 2017). "Positive ATP1B3 staining was detected in 66.7% (20/30) of the gastric cancer tissues and in only 36.7% (11/30) of the matched adjacent normal tissues (P<0.05)." (PMID 29137423, 2017). "ATP1B3 protein expression was increased in gastric cancer cells compared with that in normal gastric epithelial cells." (PMID 29137423, 2017). "To verify the oncogenic function of the ATP1B3 protein product in gastric cancer, we evaluated its expression in 30 primary gastric cancer tissue samples and matched normal tissue samples by IHC staining." (PMID 29137423, 2017). "ATP1B3 expression was elevated at both the mRNA and protein levels in gastric cancer cell lines relative to those in a normal gastric epithelial cell line." (PMID 29137423, 2017). "Together, these results indicated that ATP1B3 is increased inhuman gastric cancer and predicts a poor outcome." (PMID 29137423, 2017). "The overall survival rate of gastric cancer patients with positive ATP1B3 expression was significantly lower than that of patients with negative expression (n=30, X2=4.173, P<0.05)." (PMID 29137423, 2017). "Altered expression of apoptosis markers, including Caspase-3, was detected in ATP1B3-silenced gastric cancer cells." (PMID 29137423, 2017). "We performed RT-PCR and Western blotting to measure ATP1B3 mRNA and protein levels, respectively, in the gastric cancer cell lines SGC-7901, MGC803, BGC-823, MKN-45, AGS and in the normal human gastric epithelial cell line GES-1." (PMID 29137423, 2017). "Western blot results suggested the PI3K/AKT signalling is significantly inactivated following ATP1B3 knockdown in gastric cancer cells." (PMID 29137423, 2017). "Together, these results indicated that ATP1B3 down-regulation in gastric cancer cells inhibits cell migration and invasion in vitro." (PMID 29137423, 2017). "We investigated the correlation between ATP1B3 protein expression and clinicopathological features of 30 gastric cancer samples." (PMID 29137423, 2017). "We verified the oncogenic function of ATP1B3 in gastric cancer and the correlation between ATP1B3 expression and clinicopathological features using immunohistochemical (IHC) staining." (PMID 29137423, 2017).
gastric cancer (continued). "To further confirm the influence of ATP1B3 on gastric cancer cell apoptosis, we knocked down ATP1B3 in SGC-7901 and MKN-45 cells." (PMID 29137423, 2017). "SGC-7901 and MKN-45 cells displayed the highest endogenous expression of ATP1B3 among the gastric cancer cell lines examined." (PMID 29137423, 2017). "Consistent with previous studies, our results showed that ATP1B3 protein was increased in multiple gastric cancer cell lines compared with the normal GES-1 cell line." (PMID 29137423, 2017). "In summary, the present study demonstrated that ATP1B3 is highly expressed in human gastric cancer tissues and cell lines and is closely correlated with the clinical features of patients with gastric cancer." (PMID 29137423, 2017). "In our study, ablation of ATP1B3 inhibited cell proliferation, colony formation, migration and invasion and induced apoptosis in human gastric carcinoma cell lines, specifically in MKN-45 cells." (PMID 29137423, 2017). "ATP1B3 mRNA was expressed in different gastric cancer cells and in GES-1 cells." (PMID 29137423, 2017). "ATP1B3 protein expression was higher in gastric cancer tissues than that in normal matched tissues." (PMID 29137423, 2017). "Therefore, we transfected gastric cancer cells with ATP1B3-siRNA1 and ATP1B3-siRNA3 for the next set of experiments." (PMID 29137423, 2017). "Notably, ATP1B3 knockdown in gastric cancer cells resulted in G2/M phase arrest, which is consistent with the role of ATP1B3 in cell cycle progression." (PMID 29137423, 2017). "Overall, our experiments demonstrated that ATP1B3 may be a potential therapeutic target in gastric cancer." (PMID 29137423, 2017). "ATP1B3 silencing suppressed proliferation and progression of gastric cancer cells." (PMID 29137423, 2017). "ATP1B3 protein expression increased with further tumour development, suggesting that ATP1B3 protein up-regulation may be a relatively late event in gastric cancer." (PMID 29137423, 2017). "Furthermore, we examined the effect of ATP1B3 gene expression knockdown on the biological behaviour of gastric cancer cells using various assays." (PMID 29137423, 2017). "Next, we adopted siRNA to knockdown ATP1B3 expression in gastric cancer cells." (PMID 29137423, 2017). "We hypothesized that the PI3K/AKT signalling pathway may be involved in the regulation of ATP1B3 in gastric cancer cell proliferation and apoptosis." (PMID 29137423, 2017). "Interestingly, ATP1B3 knockdown significantly inhibited cell proliferation, colony-formation ability, migration, and invasion and increased apoptosis in human gastric carcinoma cell lines." (PMID 29137423, 2017). "Furthermore, we demonstrated that ATP1B3 silencing decreased the expression of phosphatidylinositol 3-kinase (PI3K), protein kinase B (AKT) and phosphorylated AKT (p-AKT), indicating that ATP1B3 regulates gastric cancer cell progression via the PI3K/AKT signalling pathway." (PMID 29137423, 2017). "Therefore, increased ATP1B3 expression may be a useful marker for gastric cancer diagnosis and prognosis." (PMID 29137423, 2017). "Furthermore, to determine whether ATP1B3 knockdown inhibits cell migration, we employed Transwell chamber-based assays to elucidate the role of ATP1B3 in gastric cancer cell migration." (PMID 29137423, 2017). "In addition, ATP1B3 could be an effective potential therapeutic target for treatment of gastric cancer." (PMID 29137423, 2017). "Our clinical findings suggested that ATP1B3 protein is increased in gastric cancer compared with paired adjacent non-malignant tissues, which indicates that the β3 subunit of Na+/K+-ATPase may play an active role in the development of gastric cancer." (PMID 29137423, 2017). "In addition, ATP1B3 was recently reported to be a novel determinant of pain variability and impairment of the Na+/K+-ATPase β subunit increased the incidence of apoptosis among leukaemia cells; however, the complete oncogenic role of ATP1B3 in gastric cancer is still unclear." (PMID 29137423, 2017).
gastric cancer (continued). "Knockdown of ATP1B3 arrested SGC-7901 and MKN-45 cells in G2/M phase and accordingly decreased the cell numbers in G0/G1 phase and S phase, suggesting that gastric cancer cells were arrested in G2/M phase after ATP1B3 knockdown." (PMID 29137423, 2017). "Moreover, the molecular mechanisms of ATP1B3 in gastric cancer cells have not yet been elucidated." (PMID 29137423, 2017). "However, whether ATP1B3 can mediate gastric cancer progression has not been determined, and the clinical relevance of ATP1B3 expression in gastric cancer is unclear." (PMID 29137423, 2017).
breast carcinoma (3 papers, 2018 to 2022). "For the MCF7 and SUM159 models, a highly sensitive and human-specific flow cytometry protocol using CD298 (also known as ATP1B3) expression was implemented, which has been used to identify human breast cancer cells in PDX mice." (PMID 30250146, 2018).
lung carcinoma (3 papers, 2013 to 2021). "Finally, the Oncomine database and GEPIA database showed that the mRNA expression of ATP1B1 and ATP1B3 are widely upregulated in various cancers, including Leukemia, Lung cancer, Lymphoma, Head and neck cancer and so on." (PMID 33868261, 2021). "Over-expression of ATP1B3 was also demonstrated in tumor cells compared to normal samples in colon and lung cancers (data not shown)." (PMID 24236063, 2013).
cervical cancer (2 papers, 2022 to 2025). A primary or metastatic malignant neoplasm involving the cervix. "Our study suggests the presence of a candidate gene signature comprising ATP1B3 and SLCO1B3 that holds predictive value for cervical cancer." (PMID 40834150, 2025). "Our results strongly suggest the presence of a candidate gene signature comprising ATP1B3 and SLCO1B3 that holds predictive value for chemoradiotherapy response in cervical cancer." (PMID 40834150, 2025).
hepatocellular carcinoma (2 papers, 2021 to 2022). A malignant tumor that arises from hepatocytes. "ATP1B3 is related to immune cell infiltration and immune-related cytokines expression in hepatocellular carcinoma." (PMID 35979430, 2022).
anaplastic carcinoma (1 paper, 2022). "Based on differentially expressed genes derived from the subclusters, gene set enrichment analysis showed that EC (ATP1B3) and EC (HSPA1B) contribute to the process of metastasis, for example, in fibrosarcoma and anaplastic carcinoma." (PMID 35265720, 2022).
asthenospermia (1 paper, 2022). "Furthermore, we observed a positive correlation between EMC10 and ATP1B3 in human sperm, while no application value was confirmed for scEMC10 in the diagnosis and treatment of asthenospermia." (PMID 36077468, 2022).
breast tumors (1 paper, 2022). "Interestingly, ATP1A1 and ATP1B1 isoforms were overexpressed in breast tumors while ATP1A2 was downregulated in breast tumors and ATP1B3 mRNA expression was unchanged." (PMID 36232400, 2022). "Among them, we found that ATP1A1, ATP1A2, ATP1B1, and ATP1B3 are highly expressed in normal breast tissue and among them, ATP1A1 and ATP1B1 are upregulated in breast tumors while ATP1A2 is downregulated and ATP1B3 is unchanged." (PMID 36232400, 2022). "On the contrary, a reduced mRNA expression was scored in ERα-positive than in ERα-negative breast tumors for ATP1B3." (PMID 36232400, 2022).
COVID-19 (1 paper, 2023). A disease caused by infection with severe acute respiratory syndrome coronavirus 2. "Notably, the gene association network of the thyroid hormone synthesis pathway showed that ATP1B3 played a key role in the pathway activity in patients with COVID-19." (PMID 37956172, 2023).
Enterovirus infection (1 paper, 2019). "Enterovirus infection can induce increased ATP1B3 levels that regulate the immune response by inducing the production of type I IFNs in RD muscle cell line and ATP1B3 protein can modulate HIV-1 restriction and NF-κB activation in a BST-2-dependent manner in Hela cells." (PMID 31331374, 2019).
glaucoma (1 paper, 2024). Increased pressure in the eyeball due to obstruction of the outflow of aqueous humor. "Although ATP1B3 has not been directly linked to glaucoma, dysregulation of ion channel activity is known to disrupt ion balance within the retinal ganglion cells, leading to oxidative stress and apoptosis, both present in glaucomatous eyes." (PMID 38742929, 2024).